ITGB1 (integrin subunit beta 1)
Description:
Integrins alpha-1/beta-1, alpha-2/beta-1, alpha-10/beta-1 and alpha-11/beta-1 are receptors for collagen. Integrins alpha-1/beta-1 and alpha-2/beta-2 recognize the proline-hydroxylated sequence G-F-P-G-E-R in collagen. Integrins alpha-2/beta-1, alpha-3/beta-1, alpha-4/beta-1, alpha-5/beta-1, alpha-8/beta-1, alpha-10/beta-1, alpha-11/beta-1 and alpha-V/beta-1 are receptors for fibronectin. Alpha-4/beta-1 recognizes one or more domains within the alternatively spliced CS-1 and CS-5 regions of fibronectin. Integrin alpha-5/beta-1 is a receptor for fibrinogen. Integrin alpha-1/beta-1, alpha-2/beta-1, alpha-6/beta-1 and alpha-7/beta-1 are receptors for lamimin. Integrin alpha-6/beta-1 (ITGA6:ITGB1) is present in oocytes and is involved in sperm-egg fusion (By similarity). Integrin alpha-4/beta-1 is a receptor for VCAM1. It recognizes the sequence Q-I-D-S in VCAM1. Integrin alpha-9/beta-1 is a receptor for VCAM1, cytotactin and osteopontin. It recognizes the sequence A-E-I-D-G-I-E-L in cytotactin. Integrin alpha-3/beta-1 is a receptor for epiligrin, thrombospondin and CSPG4. Alpha-3/beta-1 may mediate with LGALS3 the stimulation by CSPG4 of endothelial cells migration. Integrin alpha-V/beta-1 is a receptor for vitronectin. Beta-1 integrins recognize the sequence R-G-D in a wide array of ligands. When associated with alpha-7 integrin, regulates cell adhesion and laminin matrix deposition. Involved in promoting endothelial cell motility and angiogenesis. Involved in osteoblast compaction through the fibronectin fibrillogenesis cell-mediated matrix assembly process and the formation of mineralized bone nodules. May be involved in up-regulation of the activity of kinases such as PKC via binding to KRT1. Together with KRT1 and RACK1, serves as a platform for SRC activation or inactivation. Plays a mechanistic adhesive role during telophase, required for the successful completion of cytokinesis. Integrin alpha-3/beta-1 provides a docking site for FAP (seprase) at invadopodia plasma membranes in a collagen-dependent manner and hence may participate in the adhesion, formation of invadopodia and matrix degradation processes, promoting cell invasion. ITGA4:ITGB1 binds to fractalkine (CX3CL1) and may act as its coreceptor in CX3CR1-dependent fractalkine signaling. ITGA4:ITGB1 and ITGA5:ITGB1 bind to PLA2G2A via a site (site 2) which is distinct from the classical ligand-binding site (site 1) and this induces integrin conformational changes and enhanced ligand binding to site 1. ITGA5:ITGB1 acts as a receptor for fibrillin-1 (FBN1) and mediates R-G-D-dependent cell adhesion to FBN1. ITGA5:ITGB1 acts as a receptor for fibronectin FN1 and mediates R-G-D-dependent cell adhesion to FN1. ITGA5:ITGB1 is a receptor for IL1B and binding is essential for IL1B signaling. ITGA5:ITGB3 is a receptor for soluble CD40LG and is required for CD40/CD40LG signaling. Plays an important role in myoblast differentiation and fusion during skeletal myogenesis (By similarity). ITGA9:ITGB1 may play a crucial role in SVEP1/polydom-mediated myoblast cell adhesion (By similarity). Integrins ITGA9:ITGB1 and ITGA4:ITGB1 repress PRKCA-mediated L-type voltage-gated channel Ca(2+) influx and ROCK-mediated calcium sensitivity in vascular smooth muscle cells via their interaction with SVEP1, thereby inhibit vasocontraction. [Isoform 2]: Interferes with isoform 1 resulting in a dominant negative effect on cell adhesion and migration (in vitro). [Isoform 5]: Isoform 5 displaces isoform 1 in striated muscles. (Microbial infection) Integrin ITGA2:ITGB1 acts as a receptor for Human echoviruses 1 and 8. (Microbial infection) Acts as a receptor for Cytomegalovirus/HHV-5. (Microbial infection) Acts as a receptor for Epstein-Barr virus/HHV-4. (Microbial infection) Integrin ITGA5:ITGB1 acts as a receptor for Human parvovirus B19. (Microbial infection) Integrin ITGA2:ITGB1 acts as a receptor for Human rotavirus. (Microbial infection) Acts as a receptor for Mammalian reovirus. (Microbial infection) In case of HIV-1 infection, integrin ITGA5:ITGB1 binding to extracellular viral Tat protein seems to enhance angiogenesis in Kaposi's sarcoma lesions. (Microbial infection) Interacts with CotH proteins expressed by fungi of the order mucorales, the causative agent of mucormycosis, which plays an important role in epithelial cell invasion by the fungi. Integrin ITGA3:ITGB1 may act as a receptor for R.delemar CotH7 in alveolar epithelial cells, which may be an early step in pulmonary mucormycosis disease progression. (Microbial infection) May serve as a receptor for adhesin A (nadA) of N.meningitidis. (Microbial infection) Facilitates rabies infection in a fibronectin-dependent manner and participates in rabies virus traffic after internalization.
Synonyms: GPIIA; CD29; FNRB; MDF2; MSK12; VLA-BETA; VLAB
Tractability: Small molecule: a drug acting on it is in phase 2 or 3 trials; a structure with a bound ligand is known; a high-quality ligand is known; it belongs to a druggable protein family. Antibody: a drug acting on it is in phase 2 or 3 trials; UniProt places it where antibodies can reach, with high confidence; its Gene Ontology location is reachable by antibodies, with high confidence; UniProt predicts a signal peptide or a membrane-spanning region; the Human Protein Atlas places it where antibodies can reach. PROTAC: UniProt records ubiquitination sites on it; ubiquitination databases record sites on it; its protein half-life has been measured; a small molecule that binds it is known. Other modalities: a drug acting on it is in phase 2 or 3 trials.
Target class: Membrane receptor
Gene: Protein-coding gene on chromosome 10 (32,887,273 to 33,005,792, reverse strand). Ensembl gene ENSG00000150093.
Subcellular location: Cell membrane; Cell projection, invadopodium membrane; Cell projection, ruffle membrane; Recycling endosome; Melanosome; Cleavage furrow; Cell projection, lamellipodium; Cell junction, focal adhesion; Note=Does not localize to focal adhesions (Isoform 2); Cell membrane, sarcolemma (Isoform 5); Cell junction
Subcellular location (Human Protein Atlas): Focal adhesion sites; Plasma membrane; Endoplasmic reticulum
Pathways (Reactome):
Signal Transduction: GPER1 signaling; MET activates PTK2 signaling; MET interacts with TNS proteins; RAC1 GTPase cycle; RAC2 GTPase cycle; RAC3 GTPase cycle; RHO GTPases Activate Formins; RHOG GTPase cycle; TGF-beta receptor signaling activates SMADs
Developmental Biology: CHL1 interactions; Developmental Lineage of Mammary Gland Luminal Epithelial Cells; Developmental Lineage of Mammary Gland Myoepithelial Cells; Developmental Lineage of Mammary Stem Cells; Differentiation of Keratinocytes in Interfollicular Epidermis in Mammalian Skin; Formation of the ureteric bud; Other semaphorin interactions; Signal transduction by L1
Extracellular matrix organization: ECM proteoglycans; Elastic fibre formation; Fibronectin matrix formation; Integrin cell surface interactions; Laminin interactions; Molecules associated with elastic fibres; Syndecan interactions
Hemostasis: Basigin interactions; Cell surface interactions at the vascular wall; Platelet Adhesion to exposed collagen
Cellular responses to stimuli: Mechanical load activates signaling by PIEZO1 and integrins in osteocytes; Turbulent (oscillatory, disturbed) flow shear stress activates signaling by PIEZO1 and integrins in endothelial cells
Disease: HCMV Early Events; Potential therapeutics for SARS
Immune System: Immunoregulatory interactions between a Lymphoid and a non-Lymphoid cell; Interleukin-4 and Interleukin-13 signaling
Cell-Cell communication: Localization of the PINCH-ILK-PARVIN complex to focal adhesions
Gene Ontology:
Molecular function: actin binding; C-X3-C chemokine binding; cadherin binding; calcium ion binding; cell adhesion molecule binding; cell adhesion receptor activity; collagen binding involved in cell-matrix adhesion; fibronectin binding; magnesium ion binding; protease binding; protein binding; protein heterodimerization activity; protein tyrosine kinase binding; protein-containing complex binding; coreceptor activity; integrin binding; integrin binding involved in cell-matrix adhesion; laminin binding; protein kinase binding; signaling receptor activity
Biological process: angiogenesis; calcium-independent cell-matrix adhesion; CD40 signaling pathway; cell adhesion; cell adhesion mediated by integrin; cell-cell adhesion mediated by integrin; cell-matrix adhesion; cell-substrate adhesion; establishment of mitotic spindle orientation; heterotypic cell-cell adhesion; integrin-mediated signaling pathway; leukocyte cell-cell adhesion; leukocyte tethering or rolling; mesodermal cell differentiation; negative regulation of anoikis; negative regulation of vasoconstriction; osteoclast differentiation; positive regulation of angiogenesis; positive regulation of apoptotic process; positive regulation of fibroblast growth factor receptor signaling pathway; positive regulation of fibroblast migration; positive regulation of GTPase activity; positive regulation of phosphatidylinositol 3-kinase/protein kinase B signal transduction; positive regulation of protein localization to plasma membrane; positive regulation of vascular endothelial growth factor signaling pathway; and 30 more
Cellular component: cell surface; cleavage furrow; cytoplasm; extracellular exosome; filopodium; focal adhesion; integrin alpha1-beta1 complex; integrin alpha10-beta1 complex; integrin alpha11-beta1 complex; integrin alpha2-beta1 complex; integrin alpha3-beta1 complex; integrin alpha4-beta1 complex; integrin alpha5-beta1 complex; integrin alpha6-beta1 complex; integrin alpha9-beta1 complex; integrin alphav-beta1 complex; melanosome; membrane; membrane raft; neuromuscular junction; perinuclear region of cytoplasm; plasma membrane; receptor complex; recycling endosome; ruffle membrane; and 20 more
Genetic constraint (gnomAD): Loss-of-function variants: 10 observed, 42.79 expected, observed/expected ratio (o/e) 0.23, 90% interval 0.14 to 0.4. The upper end of that interval is the gene's LOEUF score, 0.4, which puts it in group 1 of 6, group 1 being the genes least tolerant of losing a copy. Missense variants: 304 observed, 563.06 expected, observed/expected ratio (o/e) 0.54, 90% interval 0.49 to 0.59. Synonymous variants: 182 observed, 187.05 expected, observed/expected ratio (o/e) 0.97, 90% interval 0.86 to 1.1.
Homologues: Orthologues: chimpanzee ITGB1 (98% identical), macaque ITGB1 (98% identical), pig ITGB1 (95% identical), dog ITGB1 (94% identical), rabbit ITGB1 (94% identical), mouse Itgb1 (92% identical), rat Itgb1 (92% identical), guinea pig ITGB1 (91% identical), tropical clawed frog itgb1 (81% identical), zebrafish itgb1a (78% identical), zebrafish itgb1b.1 (66% identical), zebrafish itgb1b (50% identical), and 3 more. Paralogues in human: ITGB2 (44% identical), ITGB7 (43% identical), ITGB3 (43% identical), ITGB5 (41% identical), ITGB6 (40% identical), ITGB4 (36% identical), ITGB8 (33% identical), ITGBL1 (16% identical).
Diseases named in the same sentence as ITGB1 in open-access papers:
ITGB1 is named in the same sentence as 270 diseases in open-access papers, as found by Europe PMC text mining. Sharing a sentence is not in itself a finding about the gene and the disease. The quoted sentences say what the papers report.
breast cancer (128 papers, 2008 to 2025). A primary or metastatic malignant neoplasm involving the breast. "Yet, we see that loss of ITGB1 phosphorylation at the NPxY sites has a profound effect on breast cancer invasion, emphasizing the importance of this poorly understood aspect of integrin biology." (PMID 40419795, 2025). "Our initial findings demonstrate that loss of ITGB1 phosphorylation reduces breast cancer invasion in vitro and in vivo." (PMID 40419795, 2025). "To examine the role of Integrin β1 in mediating the connection between the remodeled heart and the tumor, we have generated a PyMT breast cancer cell line with a loss of function mutation of Integrin β1 (PyMT ITGB1 KO)." (PMID 38139195, 2023). "High expression of ITGB1 is associated with a poor prognosis of colorectal, lung, and breast cancer, cancer recurrence, and cancer angiogenesis." (PMID 35648752, 2022). "hMENA silencing in lung and breast cancer cell lines caused a significant reduction in surface α3, α6 and β1, with diminished ITGB1 (β1 gene) mRNA levels." (PMID 36238292, 2022). "The β1 integrin subunit encoded by the ITGB1 gene is one member of this large family and is a critical mediator of breast cancer initiation and progression." (PMID 33747911, 2021). "ITGB1 was associated with EMT of breast cancer and the ITGB1/FAK/Src/AKT/β-catenin/MMP-9 signaling axis was an important signaling pathway." (PMID 33796128, 2021). "Both the RGDS and GFOGER peptides are known to bind integrin β1 (ITGB1), which is associated with proliferation and metastasis of breast cancer cells and a poor prognosis in patients." (PMID 31069334, 2019). "An up-regulation of ITGB1 is associated with a pro-metastatic behavior, for example in lung and breast cancer, as well as renal cell carcinomas." (PMID 29783778, 2018). "Furthermore, ITGB1 is implicated in lymphatic vascular development and lymphangiogenesis under both physiological and pathological conditions, such as breast cancer." (PMID 36632222, 2023). "Likewise, ITGB1 has been shown to be a tumor suppressor in breast cancer and PrCa when associated with α2 subunits forming the heterodimeric α2β1 integrin, a receptor for collagen and other matrix molecules, regulating the early steps of metastasis." (PMID 35202085, 2022). "Moreover, overexpression of ITGB1 was also shown to be associated with high matrix stiffness and poor overall survival in breast cancer patients." (PMID 36293493, 2022). "Elevated expression of ITGB1 and activation of ITGB1-coupled signaling have been implicated in the induction and propagation of a wide variety of human cancers and targeted disruption of ITGB1 has shown to inhibit both the initiation and maintenance of mammary cancer growth in vivo." (PMID 22920603, 2012). "Cumulatively, these data demonstrate the importance of the ITGB1 NPxY sites as essential mediators of effective breast cancer invasion." (PMID 40419795, 2025). "In the cytokine module, SDC4 and ITGB1 were identified as more active signaling pathways in breast cancer with high RiskScore." (PMID 40337509, 2025). "Our data are in line with previous findings distinguishing a key role of integrins, such as ITGB1, for tumor metastasis in breast cancer." (PMID 38775153, 2024). "Collectively, the ITGB1 KO PyMT breast cancer cell line with low aggressive tumor properties was able to recapitulate the beneficial phenotype in the MDX mouse model." (PMID 38673859, 2024). "Unlike with ITGB3, we observed a strong, positive correlation between IGF-1R and ITGB1 protein expression in basal-like breast cancer patients." (PMID 39608716, 2024). "Overall, these data indicate that ITGB1 protein expression correlates with IGF-1R protein expression in breast cancer, particularly the basal-like subtype, and that high ITGB1 expression coincides with intracellular/Golgi-localized IGF-1R in migratory cells." (PMID 39608716, 2024).
breast cancer (continued). "In vitro studies show that Fascin directly affects the expression of ITGB1 in breast cancer, thereby affecting the self-renewal capacity of breast cancer cells and their resistance to chemotherapy." (PMID 39239559, 2024). "In breast cancer (BC), the transcription of ITGB1 is activated by CDC42, FOXM1, HIF1α, and EZH2 to support the ability of BC cells to invade and spread." (PMID 38279122, 2024). "For example, in breast cancer cells, ITGB1 was identified as participating in adhesion to various extracellular matrices, self-renewal, and chemoresistance." (PMID 39180549, 2024). "USP22 and Fascin regulate the transcription of ITGB1, influencing the self-renewal and metastasis of breast cancer stem cells." (PMID 39239559, 2024). "At present, the available data show that Linc is highly effective in breast cancer and gallbladder cancer, and ITGB1-mediated cell migration and invasion are involved in the epithelial-mesenchymal transformation process." (PMID 39258668, 2024). "Previous studies have implicated crosstalk between ITGB1 and IGF-1R in response to IGF-1 stimulation, particularly in breast cancer and prostate cancer cells." (PMID 39608716, 2024). "First, we assessed ITGB1 protein expression in a panel of breast cancer cell lines and also in migratory HeLa and fibroblast cell lines." (PMID 39608716, 2024). "According to the TCGA PanCancer Atlas—Breast Invasive Carcinoma dataset, ITGB1 is strongly coexpressed with the IGF-1R in basal-like breast cancer patient tumor tissue." (PMID 39608716, 2024). "Together, our data identified a novel WAVE2/miR-29/ITGB1 signaling axis that regulates the invasion-metastasis cascade in breast cancer." (PMID 36968231, 2023). "Here, we found four upregulated hub genes (RPSA, SEC61A1, ITGB1, PSMB5) and three downregulated hub genes (PSME3, SNRNP70, SRSF3) that are significantly associated with poor overall survival of breast cancer patients." (PMID 36293493, 2022). "In the present study, we found that EZH2 upregulated ITGB1 transcription in breast cancer cells by functioning as a transcriptional co-factor of RNA Pol II to facilitate its binding to the ITGB1 promoter." (PMID 35538070, 2022). "We have previously shown that the action of DDR2 in breast cancer CAFs is important for ITGB1 activity." (PMID 35884543, 2022). "ITGB1 (integrin β1) is highly expressed in invasive breast cancer cells and plays a crucial role in breast cancer cell migration." (PMID 35433636, 2022). "ITGB1 was identified as a predictive neo-adjuvant chemotherapy resistance marker for pathological response in breast cancer." (PMID 36293493, 2022). "Some studies indicated that down-regulation of ITGB1 triggered lung disease and even cancer, such as colon cancer and breast cancer." (PMID 36232605, 2022). "ITGB1 expression is known to be of prognostic significance in breast cancer where overexpression correlates with poor survival." (PMID 34582708, 2021). "Overexpression of lnc005620 promoted the level of ITGB1, indicating that lnc0065620 regulated carcinogenesis and epirubicin resistance by targeting ITGB1 in breast cancer." (PMID 33747911, 2021). "The prominent role of MUC1 in E. coli inv invasion was unexpected, as E. coli inv has not been reported to interact with MUC1 directly and MUC1 overexpression in breast cancer cells prevents ITGB1-mediated cell adhesion to extracellular matrix components." (PMID 33824202, 2021). "In the same way, knockout of integrin beta 1 (ITGB1) has been shown to impair breast cancer initiation." (PMID 33803301, 2021). "ITGB1 is involved in regulating the invasion, angiogenesis and metastasis of various epithelial malignancies such as gastric cancer, breast cancer and glioblastoma." (PMID 34326374, 2021). "COL1-binding of MDA-MB-231 and MCF-7 breast cancer cells is mainly dependent on β1-integrins (ITGB1)." (PMID 32668815, 2020).